CD44 (CD44 molecule (IN blood group))
Diseases named in the same sentence as CD44 in open-access papers (continued):
Sharing a sentence is not in itself a finding about the gene and the disease.
breast carcinoma (continued). "ZFHX3 also enhanced breast cancer stemness, as indicated by ZFHX3-induced increases in mammosphere formation and the populations of ALDH+ or CD44+/CD24− cells, and cancer stemness is crucial for tumor initiation and progression." (PMID 33217982, 2020). "Previously, the prognosis for breast cancer was predicted using CSC markers such as ALDH1 and CD44+/CD24−." (PMID 32957507, 2020). "The results of our previous experiment with clove buds showed a significant decrease in CD24 and CD44 expression, and on the other hand, an increase in ALDH1A1 expression in treated mammary carcinomas." (PMID 32204409, 2020). "Breast cancer was the first solid tumor where CSC was identified, and the markers used to identify them in this disease are CD24/CD44 and aldehyde dehydrogenase (ALDH)." (PMID 31924241, 2020). "In breast cancer, CD24−/CD44+ CSCs were evaluated by flow cytometry before and after treatment only in a neoadjuvant trial where, similar to our study, a proportion of patients showed no detectable CD24−/CD44+ at baseline." (PMID 31924241, 2020). "Since then, the CD44+/CD24- phenotype and high ALDH activity have become the “gold standard” signature for breast cancer stem cells." (PMID 33488948, 2020). "In the context of breast cancer, STAT3 signaling has been shown to be required for maintenance of self-renewal and growth of CD44+ breast CSCs." (PMID 33335857, 2020). "Both MDA-MB-231 and MDA-MB-468 are mammary tumor cells, and the CSC subpopulation of each is described as CD44+/CD24−42." (PMID 33106480, 2020). "It has been reported that tamoxifen-resistant MCF7-LR breast cancer cells exhibited elevated expression of GRP78 and CD44." (PMID 31416894, 2019). "CDK2 inhibitor can selectively target CD44+CD24- subpopulation and restores chemo-sensitivity in breast cancer." (PMID 31120927, 2019). "In breast cancer, cells with an EMT phenotype can be inhibited by Abs specific for CD44; knockdown of CD44 induces differentiation of breast CSCs and is a promising differentiation therapy." (PMID 30899759, 2019). "Since then, the CD44+/CD24− phenotype and high ALDH activity have become the “gold standard” signature for breast cancer stem cells (BCSCs)." (PMID 31324052, 2019). "In breast cancer patients, several differentially expressed genes, involved in EMT, were identified in CTC, including UPA, IGFR1, VEGFR1, and CD44, and their expression was correlated with tumor grade and metastasis." (PMID 30959764, 2019). "Mammary stem cell markers or combined markers have been certified in different stages of stem cells in breast cancer, including ALDH, CD44, CD24, ITGA6/EpCAM, and PROCR." (PMID 31340763, 2019). "Previous studies have reported that IL-6 induced CD44+ cells with stem-like and EMT properties in breast cancer." (PMID 30989585, 2019). "In conclusion, detection of TWIST1 overexpression and stem-cell (CD24, CD44, ALDH1) transcripts in the EpCAM+ CTC fraction provides prognostic information in early stage breast cancer patients." (PMID 31261917, 2019). "In order to identify CTC subsets with properties related to breast cancer dormancy, CTC subgroups were selected for EpCAM and CD45 negativity and positivity for the CD44+CD24− stem cell signature, and the combinatorial expression of uPAR and int β1." (PMID 30959764, 2019). "Further study suggests that expression of stem cell markers including Oct4, Sox2, Nanog, and CD44 are also significantly downregulated and epithelial-to-mesenchymal transition (EMT) is also suppressed after doxycycline treatment in breast cancer." (PMID 31336613, 2019). "Curcumin, an active ingredient of turmeric, diminished self-renewal capacity of CD44+ EpCAM+ pancreatic cancer cells in vitro and in vivo and reduced proliferation and mammosphere formation of ALDH1+ breast cancer cells." (PMID 30967773, 2019).
breast carcinoma (continued). "This was further confirmed by demonstrating a correlation between reduced survival in pure HER2 breast cancer patients and expression of PYK2 and the stem cell marker CD44." (PMID 31118051, 2019). "In breast cancer cell lines, PARP inhibitor (Olaparib) can significantly decrease the proportion of BCSCs with CD44+/CD24−/low/ESA+ cell surface marker, indicating the potential activity of PARP inhibitor in anticancer stem cells." (PMID 31555586, 2019). "Next, we investigated the expression status of the Notch-1, β-catenin, STAT3, CD44, and CD24 markers in doxorubicin resistantMCF7 breast cancer cells (MCF7_DoxR) compared to MCF7 parental cells (MCF7_DoxS)." (PMID 31357721, 2019). "The most well-documented epithelial CSC markers in breast cancer are isoforms of aldehyde dehydrogenase (ALDH), while the mesenchymal CSC are characterized as CD44+ and CD24−30,31." (PMID 31092822, 2019). "The expression two antigens CD44 and CD24 has recently been used to explain the CSC population in breast cancer and ovarian cancer." (PMID 30818864, 2019). "A subset of TISCs, CD44+CD90+TISCs, which have been shown to be in direct contact with CAFs in breast cancers are thought to have enhanced tumor invasive functionality." (PMID 31106150, 2019). "In breast cancer, TAMs can promote BCSCs through a paracrine EGFR/Stat3/Sox-2 signaling pathway, while upregulation of HAS2 (hyaluronan synthase 2) in CD44+/CD24−/ESA+ BCSCs can enhance the interaction between BCSCs and TAMs, resulting in the BCSC growth." (PMID 31555586, 2019). "Breast cancer cells resistant to treatment of SAHA, a HDAC inhibitor, also express higher CD44 protein expression." (PMID 30935014, 2019). "In breast cancer, CD24−/CD44+ mesenchymal CSCs are typically located toward the invasive edge of the tumor by the tumor-stroma interface, while ALDH1+ CSCs are found in the more interior region." (PMID 31121840, 2019). "There are two major cancer stem-like cell subpopulations in human breast cancer: ALDH+ and CD44+/CD24−." (PMID 31695034, 2019). "Regarding CD44, its overexpression has been shown to upregulate the glycolysis enzyme PFKFB4, and in line with this, CD44 knock-down in breast cancer cell lines led to reduced glycolysis and AKT activity." (PMID 31661927, 2019). "Expression of VIM, CDH1, CDH2, PLS3, CXCR4, CD44 and NANOG have been found in healthy controls and the maximal expression levels of these genes were the threshold beyond which CTCs-EBF of breast cancer patients were considered positive." (PMID 30634453, 2019). "Human breast cancer cells express both CD24 and CD44, but MDA-MB-231 cancer cells expressed a high level of CD44 and a very low level of CD24." (PMID 31658701, 2019). "CD44+CD24− is a well‐known surface maker for the isolation and identification of BCSCs in breast cancer tissues and cell lines." (PMID 31599500, 2019). "In this study we evaluated for the first time the prognostic significance of TWIST1, CD24, CD44, and ALDH1 transcript quantification in EpCAM-positive circulating tumor cells isolated from peripheral blood of early stage breast cancer patients." (PMID 31261917, 2019). "For instance, a clinical pilot study shows that doxycycline, a Food and Drug Administration (FDA)-approved antibiotic, effectively reduces cancer stem cells, with a decrease of stem cell markers CD44 and ALDH1 expression, in early breast cancer patients." (PMID 31336613, 2019). "The NRF2-inducer sulforaphane, a dietary component from broccoli, inhibited self-renewal capacity of CD44+ LDH1+ pancreatic and ALDH1+ breast cancer cells in vivo and in vitro." (PMID 30967773, 2019). "In plasma membrane of breast cancer cells, 25 proteins get 27 N-glycosylation sites, such as BRCA-1, CD44, EGFR, can influence invasion and metastasis of breast cancer by regulating differentiation and proliferation of tumor cells." (PMID 31341840, 2019).
breast carcinoma (continued). "Some of these markers and combined markers (i.e., CD44+/CD24low ALDH+ and ITGA6+) are considered to correlate with poor prognosis in breast cancer, because they also identified a BCSC subpopulation." (PMID 31340763, 2019). "In this study, it was also found that the CD44+ and CD24- phenotype is equally distributed among ALDH-positive and ALDH-negative MDA-MB-468 breast cancer cells." (PMID 30845764, 2019). "In breast cancer patients, the cooperation of AF1q with TCF7 led to the transcription of CD44, which is a WNT target gene that is essentially involved in tumor progression and epithelial-to-mesenchymal transition." (PMID 31671695, 2019). "The sorted and unsorted fractions of breast cancer cells via CD44, CD24, ALDH, mammospheres, and adherent cell cultures of breast cancer cell lines were analyzed for DNA profiling by array CGH and methylation profiling." (PMID 31013960, 2019). "This review will discuss some recent progresses about the alternative splicing regulators such as CD44, heterogeneous nuclear ribonucleoprotein M (hnRNPM), SND1 and MTDH etc. in breast cancer metastasis." (PMID 31737791, 2019). "Transition was also reflected by CD44 and CD24 gradual changes (stemness markers often used in breast cancer EMT studies), patterning four readily observed gating populations." (PMID 31811131, 2019). "Exposure of tumor cells to both cytokines TGFβ and TNFα induced EMT and generated cells with a stable breast cancer stem cell phenotype, enriched in CD24−low/CD44+ cells, with a shift to the claudin low molecular subtype." (PMID 30959764, 2019). "It has been reported that these cells are enriched in both CD44+/CD24− and ALDH1+ breast cancer stem cells." (PMID 31728117, 2019). "Our studies uncovered previously unidentified functions of csGRP78 in regulation of CD44 homeostasis, cell adhesion, and cell spreading, and our findings could have important therapeutic implications for blocking CD44v functions by targeting its partner protein in tamoxifen-resistant breast cancer." (PMID 31416894, 2019). "Breast cancer stem-cell-specific markers include BMI-1, CD24, CD44, CD49f, aldehyde dehydrogenase (ALDHA1), and EpCAM." (PMID 31195298, 2019). "The aim of the current study was to evaluate the prognostic significance of TWIST1, CD24, CD44, and ALDH1 mRNA quantification in EpCAM-positive circulating tumor cells from early stage breast cancer patients with a long follow-up." (PMID 31261917, 2019). "So, in this study the status of CD24-CD44 breast cancer stem cell markers was studied in MDA-MB231 triple negative breast cancers and due to absolute dominance of CD44+CD24low/- phenotype (96.3%±1.7), the cell line was used without further cell sorting." (PMID 31870099, 2019). "The specific and strong binding of HA to CD44 receptors followed by endocytosis resulted in high transfection of the constructed micelles in CD44-positive MDA-MB-231 and MCF-7 breast cancer cells." (PMID 30943985, 2019). "Using CD44 as a biomarker to select breast cancer stem cells for single-cell sequencing, we have demonstrated that CD44GFP-high breast cancer MCF7 cells consist of multiple subpopulations with marked heterogeneity." (PMID 31811139, 2019). "Analyses of the relationship between CD44+/CD24− and TS+ in breast cancer cells, we observed a substantially higher percentage of CD44+/CD24− cells in TS+ cells than in TS− cells." (PMID 31253779, 2019). "CD44 and CD24 are considered putative stem cell markers and expression profiling of selected breast cancer cell lines in this study correlates well with previously performed studies on the same cell lines." (PMID 31430931, 2019). "Breast cancer cells with high expression of CD44, one of cancer stem cell markers, express higher levels of STAT1 compared with cells with low CD44 expression." (PMID 30709063, 2019).
breast carcinoma (continued). "This study aimed to characterize T. vulgaris effects on the expression of CSC-like markers in the chemoprevention model of breast carcinogenesis and a significant decrease in CD44 and ALH1A1 expression in rat mammary tumors was found." (PMID 30970626, 2019). "High levels of YAP/TAZ expression are associated with reductions in metastasis-free survival in patients with breast cancer and adverse features of the disease; TAZ is essential for sustaining the self-renewal of CD44+CD24−/low BCSCs." (PMID 31336602, 2019). "In luminal ER+ breast cancer models, activation of AURKA is required to induce EMT and clonal expansion of CD44+/CD24low/− cells, thus driving tumor progression." (PMID 29289986, 2018). "To validate the expression levels of the USP37 gene in breast cancer stem cells, we isolated CD24−/CD44+ cell populations from MCF-7 cell lines by magnetic activated cell sorting (MACS)." (PMID 30482232, 2018). "In human breast cancers, CSCs were first identified by the profile of expression of the cell surface marker CD24−/CD44+." (PMID 29568355, 2018). "HA and CD44 interaction activated an ErbB2-containing signaling complex, stimulating PI3K activity in multidrug-resistant human breast carcinoma cells." (PMID 29747682, 2018). "Notch1 inhibition increased chemotherapy efficacy in TNBC BCSCs (CD44+/CD24−/low population) in vitro and in a patient-derived xenograft breast cancer model." (PMID 30515368, 2018). "In breast cancer, EMT-type CSCs with high CD44 but low CD24 in the invasive front and MET-type CSCs expressing high level of ALDH1 in the tumor interior co-exist." (PMID 30038266, 2018). "Pre-operative treatment with oral doxycycline (200 mg per day) for 2 weeks is sufficient to reduce both CD44 and ALDH1 expression in tumor tissue from early breast cancer patients." (PMID 30364293, 2018). "As such, here we evaluated the ability of doxycycline to target CSCs in breast cancer patients in vivo, using well-established CSC markers (CD44 and ALDH1) as a read-out." (PMID 30364293, 2018). "Combined treatment of breast cancer cells with curcumin and epigallocatechin gallate (EGCG) reduced CD44-positive CSC population and decreased phosphorylated STAT3 expression." (PMID 29747682, 2018). "In addition, knockdown of ERα expression with ERα‐shRNA significantly decreased the number of viable ZR‐75‐1/R and MCF‐7/R cells, indicating that IBC could down‐regulate CD44 expression by the ERα pathway to sensitize of resistant breast cancer cells to paclitaxel." (PMID 30179299, 2018). "The current study aimed to investigate the association between tamoxifen resistance and breast cancer stem cells and clinical implications of CD44/CD24 and ALDH1, potential markers for breast cancer stem cell." (PMID 29416796, 2018). "Knock-down of CD44 decreased mRNA expression of MMP9, MMP14, and urokinase plasminogen activator (uPA) and inhibited cancer cell invasion in the basal-like human breast cancer cells." (PMID 29747682, 2018). "In subsequent studies, CD44+/CD24-/low and aldehyde dehydrogenase (ALDH) 1 were suggested as potential candidates for breast cancer stem cell markers." (PMID 29416796, 2018). "Interactions among hyaluronan, CD44, and CD147 also contributed to the glycolytic phenotype of breast cancer cells." (PMID 29747682, 2018). "In endocrine-resistant, ER+ breast cancer models, alisertib, a selective inhibitor of AURKA, was found to reverse stemness reprogramming and thereby restore the CD44−/CD24+ phenotype, ERα expression, and sensitivity to endocrine therapy." (PMID 29289986, 2018). "CD44 isoform switching from expressing CD44v to CD44s is essential for EMT and breast cancer progression." (PMID 29747682, 2018). "In breast cancer, previous studies have reported that the activation of the TGF-β pathway can enrich CD44+ BCSCs." (PMID 29780673, 2018).
breast carcinoma (continued). "Assessment of the expression of other BCSC markers -ALDH1A1, EpCAM, CXCR4, and CD133 in stable NRF1 overexpressing CD44+CD24− and CD44+CD24+ subpopulations showed as many as 10 different downstream breast cancer progenitor cell subpopulations." (PMID 30486409, 2018). "Later, in an independent study, it was shown that WNT5A signaling impairs CD44-AKT signaling, leading to impaired breast cancer cell migration and invasion." (PMID 30171384, 2018). "Using the same rat model, cloves significantly decreased CD24 and CD44 markers, however increased ALDH1 expression in mammary carcinoma cells." (PMID 30092754, 2018). "Breast cancer cells that demonstrate high activity of ALDH and high expression of CD44 are more resistant to both chemotherapy (doxorubicin/paclitaxel) and radiation." (PMID 30308036, 2018). "Based on previous studies on breast cancer reporting that CD44+ CSCs expressed also the oncogene c-MET, and its inhibition blocked bone metastases from breast cancer, we tested a selective c-MET inhibitor." (PMID 29461491, 2018). "Head and neck cancer stem cells are defined by markers CD44, CD133, ALDH and c-MET, whilst breast cancer cells are defined by markers CD24, CD44, CD133, EPCAM, PIWIL2 and ALDH." (PMID 30513961, 2018). "In breast cancer, Notch-ICD transactivates SOX2, which increases sphere formation, and expansion of ALDH1+ and CD44+ cells." (PMID 30211160, 2018). "We further analyzed additional breast cancer cell lines, SCP28, MDA-MB-231 and BT20, for the expression of CD44v in CD24-/CD44+ population." (PMID 28300837, 2017). "Other cell surface markers, like CD49f and CD133, can, when combined with CD44+ and CD24−, be used to identify BCSCs in different breast cancer subtypes." (PMID 29258583, 2017). "CSCs can be identified by various functional assays, including tumor sphere formation, xenograft assays, or detection of specific cell-surface markers [e.g., CD44, CD24, Oct-4, and ALDH1 in the case of breast cancer stem cells (BCSCs)]." (PMID 29228728, 2017). "Although CD44 and CD24 are well-established markers of breast cancer stemness, they are not universal surface markers for the definitive characterization of a breast cancer stem-like phenotype." (PMID 29207686, 2017). "This is expected as it has been demonstrated that basal-subtypes of breast cancer, for instance, MDA-MB-231 cells are predominantly CD44+." (PMID 28717596, 2017). "Our results, together with other reports, suggest that high CD44/CD24 ratio and ALDH1+ are indicators for breast cancer malignancy." (PMID 29062075, 2017). "A variety of drug-loaded nanoparticles conjugated with antibodies to these markers (CD44, CD133, and ABCG2) have been developed that improve the drug delivery efficiency to CSCs in colon cancer, breast cancer, and multiple myeloma." (PMID 28400729, 2017). "The interdependent down-regulation of EGFR, CD44 and EMMPRIN in the three breast carcinoma cell lines attenuated the invasion tendency, as demonstrated by the scratch test and zymography although this effect was less evident in MDA-MB-231 cells." (PMID 28465354, 2017). "Moreover, considering the high heterogeneity in CD44 isoforms expressed by CSCs, which has been documented in breast cancer, it is also plausible that regulation of CD44 splicing may allow CSCs to maintain the hybrid E/M state that has been correlated with higher stemness and tumorigenicity." (PMID 28137272, 2017). "In this study, we investigated the expression of CD44, CD24 and ALDH1 in different subtypes of breast cancer, and explored the correlation between them and cancer progression both in vitro and in vivo." (PMID 29062075, 2017).